IL6 (interleukin 6)
Diseases named in the same sentence as IL6 in open-access papers (continued):
Sharing a sentence is not in itself a finding about the gene and the disease.
lung adenocarcinoma (continued). "The positive correlation found in the lung adenocarcinoma data from TCGA between the expression of IL-6 and CD155 suggests an interplay between the expression of these molecules." (PMID 39596207, 2024). "The addition of IL-6 to M2-like macrophages significantly promoted the proliferation, invasion, and migration ability of lung adenocarcinoma cells." (PMID 38424624, 2024). "Since we found a positive correlation between the expression of these molecules, we analyzed the effect of IL-6 stimulation on CD155 expression in the four lung adenocarcinoma cell lines." (PMID 39596207, 2024). "We corroborated this analysis by demonstrating a positive correlation between tumorous IL-6 expression and a previously defined adenosine pathway signature in a TCGA cohort of lung adenocarcinoma." (PMID 37852738, 2023). "Baseline tumor bulk RNA sequencing (RNA-seq) of lung adenocarcinomas (LUADs) treated with pembrolizumab (cohort B, n=59) was used to evaluate differential expression of purine metabolism, as well as correlate IL-6 expression with PFS." (PMID 37852738, 2023). "Similar to IL-6, Panx1 mRNA was strongly expressed in poorly differentiated lung adenocarcinomas but was only weakly expressed in their well differentiated counterparts." (PMID 37696858, 2023). "Altogether, our results uncovered the NTS-CPS1 regulatory axis, consisting of AFF1 as the master transcription suppressor and IL6 as the antagonist in lung adenocarcinoma cells." (PMID 33493519, 2021). "In summary, our study finds a significant decrease in IL-6 expression of early lung adenocarcinoma with GGO, along with the level of NK cells." (PMID 34568032, 2021). "We analyzed the RNA sequencing data of surgical specimens from 21 patients with GGO-featured primary lung adenocarcinoma and verified the changes in the expression of IL-6 and other important immune molecules in the TCGA and GEO databases." (PMID 34568032, 2021). "We also detected the positive regulation of IL-6 biosynthesis in female lung adenocarcinoma patients, with increased IL-6 levels correlating with worse prognosis in NSCLC patients in previous studies." (PMID 33526761, 2021). "Nevertheless, MCP-1 and IL-6 have been reported to play important roles in the control of malignant pleural effusion and survival in mice and patients with primary lung adenocarcinoma." (PMID 32487125, 2020). "In a cohort of patients with lung adenocarcinoma treated with conventional chemotherapy, changes in pro- and anti-inflammatory cytokines, mainly IL-6, the NLR, and SII, were studied." (PMID 33167343, 2020). "Here, we detected IL-6 in various histologic subtypes of lung adenocarcinoma and found that IL-6 staining intensity was stronger in the tumor than the tumor stromal cells." (PMID 33167343, 2020). "For example, preclinical findings have identified that inhibition of the interleukin-6 (IL-6)/STAT3 pathway can also inhibit tumor growth with EGFR mutation in NSCLC and suppress KRAS-driven lung adenocarcinoma." (PMID 33537237, 2020). "C/EBP beta induces elevated IL-6 expression levels frequently observed in human lung adenocarcinomas and interacts with peroxisome proliferator-activated receptor-gamma (PPARG) involved in pathways of transcriptional misregulation in cancer." (PMID 32983988, 2020). "Here, IL-6 production by tumor cells was assessed in a cohort of patients with lung adenocarcinoma treated with conventional therapy." (PMID 33167343, 2020). "Systemic and pulmonary IL-6 are elevated in lung adenocarcinoma patients and are related to poor patient survival." (PMID 30931929, 2019). "This relationship of IL-6 with TIMP-1 expression was evident in primary tumor tissues of lung adenocarcinoma." (PMID 31443242, 2019). "We have also demonstrated that YAP1 induces STAT3 phosphorylation in lung adenocarcinoma cells by increasing expression of interleukin-6 (IL-6) (manuscript under review)." (PMID 31137841, 2019).
lung adenocarcinoma (continued). "Our findings demonstrate that E2 stimulates IL6 expression to promote lung adenocarcinoma progression through the ERβ pathway." (PMID 29970138, 2018). "In the corresponding murine KP lung adenocarcinoma cell lines, the expression of Il6 and Ifng was increased." (PMID 30190790, 2018). "It is also observed that IL-6 expression increased TIMP-3 methylation in lung adenocarcinoma and also increased cyp enzymes methylation in colon cancer." (PMID 29467412, 2018). "Immunohistochemically, higher level of TNF-α and IL-6 expressions in cancer cell were observed in AFG1-induced lung adenocarcinoma." (PMID 28801561, 2017). "In a xenograft model of lung adenocarcinoma, injection of cancer cells that stably overexpress IL‐6 leads to the formation of tumors with EMT characteristics (E‐cadherin loss and vimentin expression) and in an increased number of lung metastases." (PMID 28599100, 2017). "Inhibition of STAT3 activity was reported to induce apoptosis in lung adenocarcinoma cells via IL6/JAK2/STAT3 signalling pathway." (PMID 28427199, 2017). "Next, we evaluated the association of IL-17 expression with IL-6, IL-8, and VEGF expression in lung adenocarcinoma tissues by qRT-PCR and IHC." (PMID 27819281, 2016). "Our results revealed that MVD was positively associated with IL-17, IL-6, IL-8, and VEGF protein expression in human lung adenocarcinoma tissues." (PMID 27819281, 2016). "Our results showed higher levels of proinflammatory (IL-2 and IL-6) and anti-inflammatory (IL-4 and IL-10) cytokines in lung adenocarcinoma patients compared with smoking subjects." (PMID 26582240, 2015). "In lung adenocarcinoma patients, compared with smoking subjects, the concentrations of IL-2, IL-4, IL-6, and IL-10 were increased." (PMID 26582240, 2015). "To examine the potential role of metformin in tumor growth and metastasis of lung adenocarcinoma, we first established stable IL-6-expressing HCC827 cells (HCC827-pSB388) by lentivirus infection." (PMID 24789104, 2014). "As expected, we found that IL-6 mRNA expression in lung adenocarcinoma tissues was much higher than in paracancerous tissues (p<0.005), similar to results reported previously." (PMID 24789104, 2014). "The correlation between IL-6 and EMT markers in clinical samples, together with the in vitro IL-6 stimulation results, strongly suggests that IL-6 is involved in EMT in lung adenocarcinoma." (PMID 24789104, 2014). "In conclusion, we demonstrated that enhanced IL-6 production, via STAT3 phosphorylation, was one of the underlying mechanisms of EMT and metastasis in lung adenocarcinoma." (PMID 24789104, 2014). "We also used immunofluorescence assays to determine the protein levels of E-cadherin and vimentin in lung adenocarcinoma tissue samples with low IL-6 or high IL-6 expression." (PMID 24789104, 2014). "This study investigated the role of IL-6 in lung adenocarcinoma cell EMT and explored the potential effects of metformin on this process." (PMID 24789104, 2014). "Collectively, these in vitro results showed that metformin inhibits IL-6-induced EMT in lung adenocarcinoma cells." (PMID 24789104, 2014). "Previously, we found that autocrine IL-6-induced Stat3 activation contributes to tumor metastasis of lung adenocarcinoma." (PMID 24086497, 2013). "The contribution of autocrine IL-6-activated Stat3 to MPE in lung adenocarcinoma is also through VEGF upregulation." (PMID 24086497, 2013). "Based on these observations and the properties of TF on increasing vascular permeability, it is possible that TF is one of the downstream targets of IL-6/Stat3 signaling, which contributes to the pathogenesis of lung adenocarcinoma and MPE." (PMID 24086497, 2013). "We have found that Stat3 activated by autocrine IL-6 mediates the generation of malignant effusion via upregulation of VEGF in lung adenocarcinoma." (PMID 24086497, 2013). "Autocrine IL-6-induced Stat3 activation has been implicated in tumor metastasis and the formation of MPE in lung adenocarcinoma." (PMID 24086497, 2013).
lung adenocarcinoma (continued). "Mutations in the kinase domain of the epidermal growth factor receptor result in STAT3 activation via the IL-6–JAK pathway in human lung adenocarcinoma." (PMID 21730976, 2011). "Inhibitors of Jak2/Stat3, MEK/Erk and PI3-K/Akt pathways down-regulated IL-6 secretion in the lung adenocarcinoma PC14PE6/AS2 (AS2) cells, which spontaneously secreted IL-6 and possessed constitutively activated Stat3." (PMID 21122157, 2010). "High IL-6 levels have been detected in serum from lung adenocarcinoma patients and correlated with poor prognosis." (PMID 19582164, 2009). "Moreover, 17β-estradiol promotes lung adenocarcinoma progression by upregulating IL6 expression through the ERβ pathway." (PMID 40017690, 2025). "Our results demonstrate that IL-6 induces CD155 expression in lung adenocarcinoma cells." (PMID 39596207, 2024). "In addition, IL-6 can activate the EMT pathway in lung adenocarcinoma and promote metastasis, whereas the use of an anti-IL-6 monoclonal antibody eliminated this effect." (PMID 38424624, 2024). "We analyzed the effect of interleukin (IL)-6 on CD155 expression in lung adenocarcinoma." (PMID 39596207, 2024). "This suggests that the impact of IL-6 on CD155 expression may be more relevant in the advanced stages of lung adenocarcinoma, in which most patients are diagnosed." (PMID 39596207, 2024). "IL-6 is a pro-inflammatory cytokine produced in the TME by stromal, immune, and tumor cells and has been associated with tumor pathogenesis, progression, and treatment resistance in lung adenocarcinoma." (PMID 39596207, 2024). "In lung adenocarcinoma, the immune stemness genes Interleukin-6 (IL-6), Formyl peptide receptor 2 (FPR2) and Relaxin-3 (RLN3) can play an important role in tumor development through cytokine-cytokine receptor interactions and neuroactive ligand-receptor interactions." (PMID 38037058, 2023). "Indeed, elevated IL-6 expression was associated with poorly differentiated (high-grade) histology, whereas IL-6 was expressed at relatively low levels in well differentiated (low-grade) lung adenocarcinomas." (PMID 37696858, 2023). "In lung adenocarcinoma clinical samples, the inverse correlation between E-cadherin and IL-6 expression, and the positive correlation between IL-6, vimentin and STAT3 protein phosphorylation confirmed the importance of the IL-6/STAT3/Snail axis described in animal models." (PMID 34361105, 2021). "First, why does IL-6 decrease occur in early lung adenocarcinoma manifested as GGO?" (PMID 34568032, 2021). "Thus, our analyses revealed a novel NTS-centered regulatory axis, consisting of AFF1 as a master transcription suppressor and IL6 as an antagonist in lung adenocarcinoma cells." (PMID 33493519, 2021). "Thus, a reduced expression of IL-1β, TNF-α, and IL-6 and an enhanced expression of IL-10 were observed in lung adenocarcinoma in mice treated with zotarolimus combined with 5-FU." (PMID 33925400, 2021). "IL-6 showed the highest increase, probably because the lung adenocarcinoma cells produced IL-6." (PMID 33167343, 2020). "Even though this study focused on lung adenocarcinoma, IL-6 could be useful as a marker of treatment response in other cancers." (PMID 33167343, 2020). "Staining for IL-6 was performed in biopsies collected from 43 patients to detect whether lung adenocarcinoma tumors, in addition to stromal cells, are a supplementary source of IL-6." (PMID 33167343, 2020). "IL-6 expression was detected immunohistochemically in lung adenocarcinoma biopsies." (PMID 33167343, 2020). "In addition, IL‐6/11 is one of the highly specific biomarkers with great accuracy for the diagnosis of lung adenocarcinoma in bronchoalveolar lavage fluid specimens." (PMID 32869505, 2020). "Based on our results, the histologic lung adenocarcinoma subtypes produce IL-6, and this cytokine may be promoting cell proliferation and tumor progression." (PMID 33167343, 2020).
lung adenocarcinoma (continued). "Therefore, it is likely that IL6 plays an important role in renal cancer metastasis as in the lungs, in which IL6 promotes lung adenocarcinoma progression and metastasis." (PMID 31636361, 2020). "Taken together, both ERβ and IL6 are important in the pathogenesis of lung adenocarcinoma." (PMID 29970138, 2018). "Pro-inflammatory signals, such as tumor necrosis factor-α (TNF-α), lipopolysaccharide (LPS), or interferon-γ (IFN-γ), promote the expression of UT, while UII induces the secretion of cytokines, such as interleukine-6 (IL-6), in UT transfected human cardiomyocytes and lung adenocarcinoma cells." (PMID 28487672, 2017). "Since various studies have now indicated an important role for the IL-6/STAT3 axis as a mediator of resistance to EGFR inhibition in lung adenocarcinomas, we have also analyzed whether IL-6 was upregulated in the cell models utilized here." (PMID 27248176, 2016). "IL-6 produced by lung tumors might explain the increase in plasma concentrations detected in lung adenocarcinoma patients." (PMID 26582240, 2015). "As expected, we found reduced E-cadherin expression and enhanced vimentin expression in HCC827-pSB388 tumors compared with HCC827 tumors, further supporting the in vitro findings that IL-6 could induce EMT of lung adenocarcinoma cells." (PMID 24789104, 2014). "Taken together, these findings suggest a role for IL-6 in the progression of lung adenocarcinoma." (PMID 24789104, 2014). "Accordingly, we examined the expression of IL-6, E-cadherin and vimentin mRNA in tissue samples from 18 cases of lung adenocarcinoma, and 6 corresponding paracancerous tissues, by quantitative PCR, and analyzed the correlation between IL-6 and E-cadherin or vimentin expression." (PMID 24789104, 2014). "In this study, we found that metformin could not only retard IL-6 enhancement of tumor growth, but also reduce tumor metastasis in lung adenocarcinoma cell-bearing nude mice." (PMID 24789104, 2014). "In addition, NE-dependent up-regulation in both protein and gene levels of VEGF, IL-8, and IL-6 was observed in human lung adenocarcinoma cells in which β-AR/cAMP/PKA signaling pathway was proved as the important mechanism." (PMID 24555849, 2014). "As we demonstrated that stimulation with IL-6 in vitro could induce EMT in lung adenocarcinoma cell lines, we speculate that there may be a correlation between IL-6 production and mesenchymal or epithelial cell markers in lung adenocarcinoma tissues." (PMID 24789104, 2014). "Together, our data revealed that autocrine IL-6 could activate Stat3 and increase the level of TF expression in various lung adenocarcinoma cell lines." (PMID 24086497, 2013). "We have also demonstrated that IL-12rb2 deficient mice develop spontaneously multiorgan lymphoid infiltrates, systemic IL-6 up-regulation and in the second year of life, lung adenocarcinomas and brochioalveolar carcinomas, possibly in relation to IL-6 over-expression." (PMID 19582164, 2009). "PPAR-γ/NF-κB axis (upstream) and the IL-6/IL-6R (downstream) signaling pathway of aquaporin 3-mediated M2 macrophage polarization could regulate the proliferation, migration, and glycometabolism of lung adenocarcinoma." (PMID 40573305, 2025). "Additionally, by targeting the oncogenic molecules family with sequence similarity 64 member A and cell-division cycle 25A/ interleukin 6, miR-99a-5p has been shown to operate as a tumor suppressor in human cases of cervical squamous-cell carcinoma and lung adenocarcinoma." (PMID 40996984, 2025). "Therefore, we inferred that downregulation of IRF8 might induce MDSC formation by activating the IL6-JAK-STAT3 pathway in lung adenocarcinoma." (PMID 39049031, 2024). "Therefore, we speculate that IRF8 may affect MDSC differentiation by regulating the IL6-JAK-STAT3 pathway in lung adenocarcinoma." (PMID 39049031, 2024).
lung adenocarcinoma (continued). "In addition, C/EBPβ-induced secretion of pro-inflammatory cytokines interleukin-6 (IL6) creates a positive feedback loop that activates the STAT3 signaling pathway in tumor-associated macrophages and promotes migration and invasion of lung adenocarcinoma." (PMID 39858431, 2024). "In this study, we explored whether IL-6 regulates CD155 expression in lung adenocarcinoma." (PMID 39596207, 2024). "In addition, to test whether IL-6 can promote the progression of lung adenocarcinoma, we used IL-6 to stimulate two different LUAD cell lines, A549 and H358." (PMID 38424624, 2024). "However, as we confirmed repeatedly, IL-6 was decreased in lung adenocarcinoma with GGO." (PMID 34568032, 2021). "IL-6 may play an important role in the tumor microenvironment of early lung adenocarcinoma." (PMID 34568032, 2021). "However, the role of IL-6 during the EMT process in lung adenocarcinoma remains poorly defined." (PMID 24789104, 2014). "Therefore, we speculate that the IL-6-induced EMT of lung adenocarcinoma cells may be due to activation of STAT3." (PMID 24789104, 2014). "In vitro studies: Treating lung adenocarcinoma cell lines (e.g., A549, H1299) with varying omega-6/omega-3 ratios to assess proliferation, apoptosis, and inflammatory markers (e.g., COX-2, IL-6)." (PMID 40535806, 2025). "The heterogeneity observed in cell lines with respect to the level of IL-6 expression and cell localization of CD155 was also observed in lung adenocarcinoma tissues." (PMID 39596207, 2024). "We found that IL-6 expression in TAMs gradually increased with tumor progression and played an important role in macrophage-mediated activation of EMT in lung adenocarcinoma." (PMID 38424624, 2024). "The expression of IL-6 and CD155 at the transcript level was evaluated in patients from the TCGA lung adenocarcinoma cohort (n = 505)." (PMID 39596207, 2024). "We performed immunohistochemistry (IHC) staining for IL-6 and CD155 in the biopsies of patients with primary lung adenocarcinoma." (PMID 39596207, 2024). "Based on the GSE164789 lung adenocarcinoma single-cell RNA-seq cohort, the variations in the expression of STAT3 and JAK1, the core genes in the IL6-JAK-STAT3 pathway, were calculated based on the developmental trajectory of MDSCs." (PMID 39049031, 2024). "In both the GSE41271 and TCGA lung adenocarcinoma cohorts, the IL6-JAK-STAT3 pathway was activated in the MDSC high infiltration group, while the IL6-JAK-STAT3 pathway was inhibited in the IRF8 high-expression group." (PMID 39049031, 2024). "IRF8 promotes MDSC formation in lung adenocarcinoma which lacks experimental verification, especially since IRF8 regulates MDSC differentiation through the IL6-JAK-STAT3 pathway, which only provides us with theoretical insights." (PMID 39049031, 2024). "This study analyzed the correlation between IL-6 and CD155 in a lung adenocarcinoma cohort from The Cancer Genome Atlas (TCGA)." (PMID 39596207, 2024). "Inhibition of the malignant progression of lung adenocarcinoma is achieved by TIFI-γ, which can regulate IL-6 transactivation by disrupting TAF15/tbp." (PMID 37573347, 2023). "In lung adenocarcinoma, the low YTHDF1 group was mainly enriched in immunity-related signaling pathways (allograft rejection, IL6-JAK-STAT3 signaling, inflammatory response, and IL2-STAT5 signaling)." (PMID 36479088, 2022). "In lung adenocarcinoma, the low YTHDF2 group was mainly enriched in immunity-related signaling pathways (inflammatory response, IL6-JAK-STAT3 signaling, allograft rejection, and IL2-STAT5 signaling)." (PMID 36479088, 2022). "Recently, Wu and colleagues demonstrated that lncRNAs LEISA accelerated the proliferation and inhibited apoptosis of lung adenocarcinoma cells in vitro and in vivo by facilitating STAT3 to transcriptionally activate IL-6." (PMID 35740511, 2022). "The ELISA assay findings demonstrated that CBX3/5 promoted and CBX7 inhibited the secretion of IL-6 and IFN-γ in lung adenocarcinoma cell lines." (PMID 34966411, 2021).